RNF41 (ring finger protein 41)
Description:
Acts as E3 ubiquitin-protein ligase and regulates the degradation of target proteins. Polyubiquitinates MYD88. Negatively regulates MYD88-dependent production of pro-inflammatory cytokines. Can promote TRIF-dependent production of type I interferon and inhibits infection with vesicular stomatitis virus (By similarity). Promotes also activation of TBK1 and IRF3. Involved in the ubiquitination of erythropoietin (EPO) and interleukin-3 (IL-3) receptors. Thus, through maintaining basal levels of cytokine receptors, RNF41 is involved in the control of hematopoietic progenitor cell differentiation into myeloerythroid lineages (By similarity). Contributes to the maintenance of steady-state ERBB3 levels by mediating its growth factor-independent degradation. Involved in the degradation of the inhibitor of apoptosis BIRC6 and thus is an important regulator of cell death by promoting apoptosis. Also acts as a PRKN modifier that accelerates its degradation, resulting in a reduction of PRKN activity, influencing the balance of intracellular redox state. The RNF41-PRKN pathway regulates autophagosome-lysosome fusion during late mitophagy. Mitophagy is a selective form of autophagy necessary for mitochondrial quality control.
Synonyms: FLRF; NRDP1; SBBI03
Tractability: PROTAC: UniProt records ubiquitination sites on it; ubiquitination databases record sites on it; its protein half-life has been measured.
Gene: Protein-coding gene on chromosome 12 (56,202,179 to 56,224,275, reverse strand). Ensembl gene ENSG00000181852.
Subcellular location (Human Protein Atlas): Nuclear bodies; Nucleoplasm; Midbody ring
Pathways (Reactome):
Immune System: Antigen processing: Ubiquitination & Proteasome degradation
Signal Transduction: Downregulation of ERBB2:ERBB3 signaling
Gene Ontology:
Molecular function: identical protein binding; protein binding; protein domain specific binding; receptor tyrosine kinase binding; small GTPase binding; ubiquitin protein ligase activity; ubiquitin-protein transferase activity; enzyme binding; erythropoietin receptor binding; interleukin-3 receptor binding; zinc ion binding
Biological process: extrinsic apoptotic signaling pathway; negative regulation of cell migration; negative regulation of cell population proliferation; positive regulation of protein catabolic process; positive regulation of reactive oxygen species metabolic process; proteasomal protein catabolic process; protein autoubiquitination; protein polyubiquitination; regulation of MAPK cascade; regulation of phosphatidylinositol 3-kinase/protein kinase B signal transduction; regulation of reactive oxygen species metabolic process; protein ubiquitination
Cellular component: endoplasmic reticulum tubular network; perinuclear region of cytoplasm; cytosol
Genetic constraint (gnomAD): Loss-of-function variants: 4 observed, 31.01 expected, observed/expected ratio (o/e) 0.13, 90% interval 0.063 to 0.29. The upper end of that interval is the gene's LOEUF score, 0.29, which puts it in group 1 of 6, group 1 being the genes least tolerant of losing a copy. Missense variants: 226 observed, 447.15 expected, observed/expected ratio (o/e) 0.51, 90% interval 0.45 to 0.56. Synonymous variants: 161 observed, 158.87 expected, observed/expected ratio (o/e) 1.01, 90% interval 0.89 to 1.15.
Homologues: Orthologues: chimpanzee RNF41 (100% identical), dog RNF41 (100% identical), macaque RNF41 (100% identical), guinea pig RNF41 (99% identical), mouse Rnf41 (99% identical), pig RNF41 (99% identical), rabbit RNF41 (99% identical), rat Rnf41 (99% identical), zebrafish rnf41 (91% identical), tropical clawed frog rnf41 (88% identical), Drosophila melanogaster elgi (57% identical). Paralogues in human: RNF151 (16% identical).
Diseases named in the same sentence as RNF41 in open-access papers:
RNF41 is named in the same sentence as 45 diseases in open-access papers, as found by Europe PMC text mining. Sharing a sentence is not in itself a finding about the gene and the disease. The quoted sentences say what the papers report.
breast carcinoma (7 papers, 2014 to 2023). "Indeed, reduced RNF41 levels have been reported in and contribute to the progression of breast cancer 24, prostate cancer 25 and brain cancer." (PMID 31754404, 2019).
colorectal cancer (3 papers, 2022 to 2024). A primary or metastatic malignant neoplasm that affects the colon or rectum. "For example, hsa_circ_0001361 has been reported to accelerate the formation and metastasis of the vascular system in oral squamous cell carcinoma, while hsa_circ_0006156 inhibited colorectal cancer stemness and metastasis via RNF41-dependent ASB6 degradation." (PMID 38802851, 2024).
hepatocellular carcinoma (3 papers, 2019 to 2024). A malignant tumor that arises from hepatocytes. "In terms of CACYBP, it has been verified that CACYBP can promote hepatocellular carcinoma progression in the absence of RNF41-mediated degradation." (PMID 33014055, 2020).
fibrosis (2 papers, 2025). the formation of excess fibrous connective tissue in an organ or tissue in a reparative or reactive process. "Recent studies have developed a gene therapy approach utilizing dendrimer–graphite nanoparticles to selectively enhance RNF41 expression in macrophages, leading to notable improvements in hepatic fibrosis and regeneration in liver injury mouse models." (PMID 40873954, 2025). "Furthermore, we systematically evaluated the clinical relevance of RNF41 methylation status by analyzing its correlation with established non-invasive fibrosis indices." (PMID 40861243, 2025).
glioblastoma (2 papers, 2022 to 2024). The most malignant astrocytic tumor (WHO grade IV). "In glioblastoma, RNF41 mediates the ubiquitination of Dvl2, leading to enhanced migration and invasion in glioblastoma." (PMID 36446779, 2022).
chronic hepatitis B (1 paper, 2025). "Patients with early-stage liver cirrhosis exhibited significantly higher methylation levels of Ring finger protein 41 promoter than chronic hepatitis B patients and health controls, accompanied by reduced mRNA expression." (PMID 40861243, 2025).
Cirrhosis (1 paper, 2025). A chronic disorder of the liver in which liver tissue becomes scarred and is partially replaced by regenerative nodules and fibrotic tissue resulting in loss of liver function. "As a non-invasive hematologic biomarker for early cirrhosis, RNF41 methylation has shown better diagnostic performance than traditional indicators such as LSM, FIB-4, and APRI scores." (PMID 40861243, 2025). "At the optimal cutoff value of 16.138%, RNF41 methylation achieved a sensitivity of 86.67% and specificity of 81.00%, indicating robust diagnostic accuracy for cirrhosis detection." (PMID 40861243, 2025). "The diagnostic performance of RNF41 PMR values in distinguishing HBV-CLC from CHB significantly outperformed conventional indices including LSM, FIB-4, and APRI scores, suggesting that RNF41 methylation status in PBMCs may serve as a promising non-invasive diagnostic biomarker for early cirrhosis." (PMID 40861243, 2025).
colon cancer (1 paper, 2023). "m6A-modified circFNDC3B plays a tumor suppressive role in colon cancer CSCs by increasing RNF41 mRNA stability and expression and thus promoting ASB6 degradation via RNF41-mediated ubiquitination." (PMID 36831219, 2023).
congenital heart disease (1 paper, 2021). A heart disease that is present at birth. "The genetic variant (rs76280383) belonging to the RNF41 gene, which is known to be associated with congenital heart diseases in the Chinese Mongolian population, was also an Asian-specific mutation." (PMID 34054925, 2021).
COVID-19 (1 paper, 2023). A disease caused by infection with severe acute respiratory syndrome coronavirus 2. "We observed a reduced plasma level of RNF41 in patients with COVID-19, suggesting a potential function of RNF41 in SARS-CoV-2 infection." (PMID 37047248, 2023).
diabetes (1 paper, 2025). "In a GWAS study of the Taiwan Biobank (TWB), four novel genes—NABP2, RASA2, RNF41, and SLC39A5—were identified for human height, and it was also discovered that these genes have associated with cardiovascular disease, diabetes, and cancer." (PMID 39910149, 2025).
esophageal adenocarcinoma (1 paper, 2020). A malignant tumor with glandular differentiation arising predominantly from Barrett mucosa in the lower third of the esophagus. "The statistically higher expressions of PLAUR, BIK, DRAM2, RNF41, STK38, ATG5, and PARP1 were measured in esophageal cancer than those in normal tissue, while statistically significant differences were also detected between ESCC and esophageal adenocarcinoma (EAC)." (PMID 32974198, 2020).
Hepatic fibrosis (1 paper, 2025). The presence of excessive fibrous connective tissue in the liver. "Compared with HC, RNF41 expression in macrophages was significantly downregulated in both cirrhotic patients and mice models of hepatic fibrosis." (PMID 40861243, 2025). "While these investigations established RNF41’s role in hepatic fibrosis through mechanisms involving macrophage phenotype switching via the C/EBP-β/PPAR-γ pathway and subsequent IGF-1-mediated HSC inactivation, they were limited to liver tissue analyses." (PMID 40861243, 2025). "These correlations suggest the potential utility of RNF41 methylation as a complementary biomarker for early liver fibrosis." (PMID 40861243, 2025). "The methylation level of the Ring finger protein 41 promoter in peripheral blood mononuclear cells of 190 participants were quantified with Methylight, and the changes of serum inflammatory cytokines related to liver fibrosis were analyzed simultaneously." (PMID 40861243, 2025).
liver cirrhosis (1 paper, 2025). "This study specifically investigates the diagnostic potential of Ring finger protein 41 promoter methylation as an epigenetic biomarker for detecting early-stage hepatitis B virus-related liver cirrhosis." (PMID 40861243, 2025). "In summary, RNF41 promoter hypermethylation in PBMCs represents a characteristic epigenetic alteration in HBV-associated liver cirrhosis patients." (PMID 40861243, 2025). "Ring finger protein 41 may play a critical role in the pathogenesis of liver cirrhosis, with its methylation status in peripheral blood mononuclear cells demonstrating strong potential as a non-invasive biomarker for early liver cirrhosis detection." (PMID 40861243, 2025).
myelodysplastic syndrome (1 paper, 2016). A clonal hematopoietic disorder characterized by dysplasia and ineffective hematopoiesis in one or more of the hematopoietic cell lines. "In a newly published paper, lenalidomide was shown to increase EPOR levels by inhibiting the E3 ubiquitin ligase RNF41 in cells from the myeloid lineage involved in myelodysplastic syndrome." (PMID 27581518, 2016).
cancer (9 papers, 2011 to 2024). A tumor composed of atypical neoplastic, often pleomorphic cells that invade other tissues. "Whether RNF41 performs a consistently inhibitory role in other human cancers awaits further investigation." (PMID 31754404, 2019).
tumor (8 papers, 2016 to 2025). "In vivo experiments showed that overexpression of circFNDC3B or RNF41 alone suppressed tumor growth, stemness, and liver metastasis through modulation of ASB6." (PMID 36831219, 2023). "Collectively, these data indicate that circFNDC3B or RNF41 overexpression suppresses tumor growth, stemness and liver metastasis via modulating ASB6 in vivo." (PMID 36446779, 2022). "In vivo experiments further showed that circFNDC3B or RNF41 overexpression repressed tumor growth, stemness and liver metastasis via modulating ASB6." (PMID 36446779, 2022). "Xenograft study revealed that overexpression of circFNDC3B or RNF41 remarkably decreased tumor volumes and weight, accompanied with increased RNF41 level in xenograft tumors." (PMID 36446779, 2022). "IHC analysis further confirmed the circFNDC3B- or RNF41-mediated downregulation of ASB6 in tumor tissues, and the proliferation marker Ki-67 and stemness marker CD133 were also reduced by circFNDC3B or RNF41 overexpression in vivo." (PMID 36446779, 2022). "Consistency was found from the study by Shao et al28 that RNF41 expression was reduced in HCC tumor tissues compared with adjacent healthy tissues." (PMID 31754404, 2019). "In summary, these findings support that RNF41 was a tumor suppressor in BCa metastasis and highlights that targeting RNF41-NUDC-β-tubulin axis could be a valuable strategy to ameliorate BCa progression and metastasis." (PMID 40494872, 2025). "Similarly, our results indicated that RNF41 may also act as a tumor suppressor by degrading CACYBP in HCC." (PMID 31754404, 2019). "Moreover, CACYBP exerts its tumor-promoting effect by releasing rapid cell cycle progression through promoting the Ser10 phosphorylation and subsequent cytoplasmic sequestration of P27Kip1, whereas RNF41 could act against CACYBP function in HCC." (PMID 31754404, 2019). "A weak but statistically significant negative association was observed when performing correlation analysis using expression scores of RNF41 and CACYBP in HCC tumor tissues." (PMID 31754404, 2019). "However, in normal hepatic cells, RNF41 promotes the degradation of CACYBP via E3 ligase activity and counteracts its tumor-promoting effect." (PMID 31754404, 2019).
infection (3 papers, 2011 to 2022). The state of being infected such as from the introduction of a foreign agent such as serum, vaccine, antigenic substance or organism. "We speculated that viral EBNA3B hijacks the ubiquitination of RNF41 by negatively interacting with PSME3, so that EBV induces other ubiquitin proteins to act at the first and second infection stages in the lytic phase." (PMID 30133498, 2018). "In addition, viral protein EBNA3B may hijack the ubiquitination function of RNF41 by negatively interacting with human protein PSME3, so that EBV exploits other ubiquitin proteins to carry out ubiquitination at both infection stages." (PMID 30133498, 2018).
RNF41 also shares sentences with these, for which no sentence is quoted: prostate carcinoma (3 papers); cervical cancer (2); glioma (2); Alzheimer disease (1); bladder cancer (1); brain cancer (1); breast tumour (1); cardiovascular disease (1); Dn (1); esophageal cancer (1); gastric cancer (1); Globozoospermia (1); heart failure (1); intracerebral haemorrhage (1); invasive breast carcinoma (1); ischemia (1); male infertility (1); male reproductive diseases (1); melanoma (1); myocardial ischemia (1); neurological diseases (1); oral squamous cell carcinoma (1); pheochromocytoma (1); reproductive disease (1); rhabdoid tumor (1); type 2 diabetes (1); virus infection (1).